PLEKHJ1 (pleckstrin homology domain containing J1)
Synonyms: GNRPX; FLJ10297
Tractability: PROTAC: ubiquitination databases record sites on it; its protein half-life has been measured.
Gene: Protein-coding gene on chromosome 19 (2,230,084 to 2,237,704, reverse strand). Ensembl gene ENSG00000104886.
Subcellular location (Human Protein Atlas): Mitochondria
Gene Ontology:
Molecular function: protein binding
Biological process: endosome organization; receptor recycling; retrograde transport, endosome to Golgi
Cellular component: early endosome; recycling endosome; trans-Golgi network; cytosol
Genetic constraint (gnomAD): Loss-of-function variants: 23 observed, 20.39 expected, observed/expected ratio (o/e) 1.13, 90% interval 0.81 to 1.59. The synonymous counts are far from expectation, so gnomAD's model fits this gene poorly and the ratio says little. Missense variants: 241 observed, 182.26 expected, observed/expected ratio (o/e) 1.32, 90% interval 1.19 to 1.47. Synonymous variants: 113 observed, 75.07 expected, observed/expected ratio (o/e) 1.51, 90% interval 1.29 to 1.76.
Homologues: Orthologues: macaque PLEKHJ1 (98% identical), pig PLEKHJ1 (91% identical), dog PLEKHJ1 (91% identical), mouse Plekhj1 (87% identical), chimpanzee PLEKHJ1 (86% identical), tropical clawed frog plekhj1 (75% identical), zebrafish plekhj1 (68% identical). Paralogues in human: PHETA1 (34% identical), PHETA2 (25% identical).
Diseases named in the same sentence as PLEKHJ1 in open-access papers:
PLEKHJ1 is named in the same sentence as 2 diseases in open-access papers, as found by Europe PMC text mining. Sharing a sentence is not in itself a finding about the gene and the disease. The quoted sentences say what the papers report.
emphysema (1 paper, 2021). "The cytosolic transport (RNF126, PLEKHJ1, VPS51, and AP1G1), target of rapamycin (mTOR) signaling (PIK3CA, STK11, RPS6KB2, and PRR5), regulation of translation, metabolic regulation, and apoptosis are involved in the percent emphysema-associated network." (PMID 34777474, 2021).
cancer (1 paper, 2021). A tumor composed of atypical neoplastic, often pleomorphic cells that invade other tissues. "Interestingly, Candesartan has been found to interact with the proteins Plekhj1, Sh2b3, and DotL1, all of which are involved in various signaling pathways in cancer cells." (PMID 33986418, 2021).